RN7SKP30 (RN7SK pseudogene 30)
Gene: Miscellaneous RNA gene on chromosome 4 (55,540,502 to 55,540,835, reverse strand). Ensembl gene ENSG00000223305.
Homologues: Orthologues: chimpanzee 7SK (82% identical). Paralogues in human: 7SK (72% identical), RN7SKP170 (72% identical), RN7SKP180 (71% identical), RN7SKP8 (70% identical), RN7SKP176 (70% identical), RN7SKP203 (70% identical), RN7SKP173 (70% identical), RN7SKP245 (70% identical), RN7SKP77 (70% identical), RN7SKP184 (69% identical), RN7SKP185 (69% identical), RN7SKP250 (69% identical), and 283 more.